TAF5 (TATA-box binding protein associated factor 5)
Description:
The TFIID basal transcription factor complex plays a major role in the initiation of RNA polymerase II (Pol II)-dependent transcription. TFIID recognizes and binds promoters with or without a TATA box via its subunit TBP, a TATA-box-binding protein, and promotes assembly of the pre-initiation complex (PIC). The TFIID complex consists of TBP and TBP-associated factors (TAFs), including TAF1, TAF2, TAF3, TAF4, TAF5, TAF6, TAF7, TAF8, TAF9, TAF10, TAF11, TAF12 and TAF13. The TFIID complex structure can be divided into 3 modules TFIID-A, TFIID-B, and TFIID-C. TAF5 is involved in two modules of TFIID, in TFIID-A together with TAF3 and TBP, and in TFIID-B with TAF8. Involved in contacts between TFIID and TFIIF in the PIC.
Synonyms: TAF(II)100; TAFII-100; TAFII100; TAF2D
Tractability: Small molecule: a structure with a bound ligand is known. PROTAC: ubiquitination databases record sites on it; its protein half-life has been measured.
Gene: Protein-coding gene on chromosome 10 (103,367,964 to 103,389,065, forward strand). Ensembl gene ENSG00000148835.
Subcellular location: Nucleus
Subcellular location (Human Protein Atlas): Nucleoplasm
Pathways (Reactome):
Gene expression (Transcription): RNA Polymerase II Pre-transcription Events; RNA Polymerase II Promoter Escape; RNA Polymerase II Transcription Initiation; RNA Polymerase II Transcription Initiation And Promoter Clearance; RNA Polymerase II Transcription Pre-Initiation And Promoter Opening; RNA polymerase II transcribes snRNA genes
Disease: HIV Transcription Initiation; RNA Polymerase II HIV Promoter Escape; Transcription of the HIV genome
Gene Ontology:
Molecular function: identical protein binding; protein binding; RNA polymerase II general transcription initiation factor activity
Biological process: DNA-templated transcription initiation; mRNA transcription by RNA polymerase II; positive regulation of transcription initiation by RNA polymerase II; regulation of transcription by RNA polymerase II; RNA polymerase II preinitiation complex assembly; transcription initiation at RNA polymerase II promoter; positive regulation of DNA-templated transcription; regulation of DNA repair
Cellular component: chromatin; nucleolus; nucleoplasm; nucleus; transcription factor TFIID complex; transcription factor TFTC complex
Genetic constraint (gnomAD): Loss-of-function variants: 19 observed, 76.13 expected, observed/expected ratio (o/e) 0.25, 90% interval 0.17 to 0.37. The upper end of that interval is the gene's LOEUF score, 0.37, which puts it in group 1 of 6, group 1 being the genes least tolerant of losing a copy. Missense variants: 845 observed, 970.83 expected, observed/expected ratio (o/e) 0.87, 90% interval 0.82 to 0.92. Synonymous variants: 382 observed, 371.41 expected, observed/expected ratio (o/e) 1.03, 90% interval 0.94 to 1.12.
Homologues: Orthologues: chimpanzee TAF5 (99% identical), macaque TAF5 (99% identical), dog TAF5 (97% identical), rabbit TAF5 (97% identical), mouse Taf5 (97% identical), rat Taf5 (96% identical), pig TAF5 (96% identical), guinea pig TAF5 (89% identical), tropical clawed frog taf5 (74% identical), zebrafish taf5 (73% identical), Drosophila melanogaster Taf5 (38% identical), Caenorhabditis elegans taf-5 (27% identical), and 1 more. Paralogues in human: TAF5L (29% identical).
Diseases named in the same sentence as TAF5 in open-access papers:
TAF5 is named in the same sentence as 5 diseases in open-access papers, as found by Europe PMC text mining. Sharing a sentence is not in itself a finding about the gene and the disease. The quoted sentences say what the papers report.
gastric cancer (1 paper, 2024). A primary or metastatic malignant neoplasm involving the stomach. "Furthermore, high expression of TAF5 has been associated with a good response in gastric cancer." (PMID 38674117, 2024).
heart failure (1 paper, 2023). Inability of the heart to pump blood at an adequate rate to meet tissue metabolic requirements. "Brightfield and fluorescent microscopy revealed classical signs of heart failure in taf5 and taf1 mutant (loss of function, null alleles) as measured by reduced ejection fraction, dimensional cardiomyocyte strain, and pericardial edema." (PMID 37746814, 2023). "Through a forward genetic screen in zebrafish, we have recovered a recessive mutant phenotype characterized by craniofacial hypoplasia, ventricular hypoplasia, heart failure at 96 h post-fertilization and lethality, and show it is caused by a nonsense mutation in taf5." (PMID 37746814, 2023). "taf5−/− zebrafish display reduced survival, heart failure, and facial and cardiac hypoplasia and fail to thrive." (PMID 37746814, 2023). "Importantly, these metabolic derangements were absent in N2:TTNa mutants with akinetic hearts indicating that metabolic impairments found in taf1 and taf5 embryos were not secondary to heart failure." (PMID 37746814, 2023).
oral squamous cell carcinoma (1 paper, 2022).
cancer (2 papers, 2024). A tumor composed of atypical neoplastic, often pleomorphic cells that invade other tissues. "RNU2-2P is a pseudogene that is involved in cancer and is inhibited by TBP, TAF5 and GTF2B." (PMID 38674117, 2024). "Our anti-TAF2 antibody was able to immunoprecipitate endogenous TAF2, as well as core subunits of the TFIID complex, including TBP, TAF4, TAF5, TAF6, and TAF7, in nuclear extracts from colorectal HCT116, embryonic kidney HEK-293, and ovarian A2780 cancer lines." (PMID 38773077, 2024).
infection (1 paper, 2022). The state of being infected such as from the introduction of a foreign agent such as serum, vaccine, antigenic substance or organism. "Although Leptospira was the infection with more genes found in the significant genomic window, few genes are linked to each other (IMPA2, MPPE1, and GNAL—TAF5 and USMG5)." (PMID 35581286, 2022).